SNAI2 (snail family transcriptional repressor 2)
Diseases named in the same sentence as SNAI2 in open-access papers (continued):
Sharing a sentence is not in itself a finding about the gene and the disease.
cancer (continued). "In contrast, AS906 and AS914, which derived from carcinomas with sarcomatoid features and formed loose spheroids in culture, expressed ZEB1, SNAI2, CD44, and Vimentin, but negligible levels of EpCAM and E-Cadherin (CDH1)." (PMID 33941777, 2021). "Paradoxically, Slug (SNAI2), which belongs to Snail transcriptional repressor family, can be downregulated by MDM2 to enhance E-cadherin expression and repress cancer invasiveness." (PMID 32477121, 2020). "Exposure of PDX-derived cancers cells to obASCs resulted in similar expression changes of Serpine1, TWIST1, and SNAI2 (8.61 fold ± 0.19, 2.60 fold ± 1.40, 6.11 fold ± 1.15, respectively)." (PMID 31118047, 2019). "SNAI2 acts as an inhibitory transcription factor that binds to E-box motifs of CDH1 and represses its transcription in cancer." (PMID 31749661, 2019). "TWIST1, SNAI2 and FOXC2 also showed moderate inverse correlations with immune cell content in four of five cancer types." (PMID 31780722, 2019). "ZEB1, ZEB2, SNAI1, and SNAI2 were significantly and positively correlated with the ESTIMATE immune score in all five cancer types examined." (PMID 31780722, 2019). "qPCR analyses revealed that the mesenchymal markers (i.e. SNAI1, SNAI2, ZEB1, ZEB2, CDH2, vimentin and fibronectin) expression was decreased in cancer EVs-exposed BRCA1-KO fibroblasts, while the expression of CDH1 was increased." (PMID 31200749, 2019). "ZEB1, ZEB2, SNAI1, SNAI2 and FOXC2 exhibited consistent positive correlations with the ESTIMATE stromal score in all five cancer types." (PMID 31780722, 2019). "E-cad is potentially repressed by Slug (SNAI2) and Snail (SNAI1), which are master regulatory transcription factors involved in the EMT of cancer cells." (PMID 30897151, 2019). "In our study, among the selected genes related to the partial processes of cancer cell invasivity, we identified higher cancer-specific methylation levels in the CXCL12, TWIST1 and SNAI2 genes." (PMID 30189837, 2018). "The relationships between the decreased methylation levels of the SNAI2 and ADAM23 genes and cancer de-differentiation and haematogenous dissemination, respectively, indicate novel functions of those genes in the invasive processes." (PMID 30189837, 2018). "In breast lines and primary cancer culture, VEGFA rapidly upregulates SOX2 expression, leading to SNAI2 induction, EMT, increased invasion and metastasis." (PMID 28504716, 2017). "We also detected upregulation of genes involved in cancer metastasis and cancer stemness (FOXC2, SNAI2, CXCRs, and IGF1), cell stemness (NANOG, POU5F1, and KLF4), metalloproteinases (MMP7, MMP10, and MMP13), and angiogenic factors (IL-8 and S1PR1)." (PMID 28423353, 2017). "Collectively, these findings showed that POU2F1 induced the transcription of Twist1, Snai1, Snai2 and ZEB1 genes which induce cancer cell EMT." (PMID 28489585, 2017). "POU2F1 induced the transcription of Twist1, Snai1, Snai2 and ZEB1 genes which induce cancer cell EMT." (PMID 28489585, 2017). "The cancer pathway finder PCR array revealed 9 genes, including ACSL4, BIRC3,CA9, CCL2, FLT1, FOXC2, G6PD, IGFBP3 and SNAI2, with significantly altered expression in the siRNA-treated MCF-7 cells." (PMID 27478411, 2016). "As SNAI2/SLUG is one of the key factors for E-cadherin suppression and for EMT, which represents a more aggressive phenotype of cancer, the results seem reasonable." (PMID 25928859, 2015). "Here we show that the onset of hypoxia-induced cancer stem cell features requires the beta-catenin-dependent post-transcriptional up-regulation of CA9 and SNAI2 gene expression." (PMID 24260469, 2013). "Transcription factors of the Twist family (Twist1, Twist2), snail family (SNAI1/snail, SNAI2/slug), as well as ZEB family (ZEB1, ZEB2), control the EMT process in cancer." (PMID 24244294, 2013).
cancer (continued). "For example, expression of SLUG/SNAI2, TWIST, CD146 and Kruppel-like factor 4 (KLF4), which promote EMT and invasion, can drive cancer cells to express the CD44+/CD24−BCSC markers and exhibit BCSC phenotypes." (PMID 24977105, 2012). "We also provide compelling evidence that the transcription factor SNAI2, in conjunction with MEK1/2 signaling, drives the hybrid EMT phenotype in TPM cancers, facilitating survival and apoptosis resistance through epigenetic suppression of apoptotic markers like BIM and BMF." (PMID 40560846, 2025). "First, we found that ZEB1, SNAI1, SNAI2, TWST1, SMAD3, and HIC1, known to be affected upon EMT in both the RPE and forms of cancer, are preferential repressors in hiPSCs compared to RPE, likely acting as preventive developmental gatekeepers under physiological conditions." (PMID 40565279, 2025). "Furthermore, although our network pharmacology analysis also identified several other potential core targets, given that SNAI2 plays a crucial role in EMT and cancer metastasis, we chose SNAI2 for further research." (PMID 41356226, 2025). "EGFR and MAPK signaling pathway components as well as the EMT transcription factor SLUG (SNAI2;) or the putative cancer stem cell marker CD44 may be considered, at least partially, as effective cancer targets or surrogate biomarkers." (PMID 38378518, 2024). "We then explored by real-time qPCR the impact of miR-662 overexpression in MDA-MB-231 cells on expression levels of well-established stemness markers that are involved in embryogenesis and cancer –NOTCH1, WNT7b, ZEB1, TCF3, CTNNB1, CD44, CD24, SNAI2, OCT-04, c-MYC, EZH2–." (PMID 37443350, 2023). "Besides, there was a robust positive relationship between SNAI2 and NRP1, and CD276 in most of the TCGA cancers." (PMID 37251370, 2023). "It is therefore not surprising that SNAI2 plays a crucial role in developmental processes such as mesoderm formation, or neural crest migration, but also in cancer." (PMID 37372403, 2023). "To determine the SNAI2 expression in cancers and their corresponding adjacent non-cancerous tissues, we employed the TCGA and GTEx datasets to analyze the SNAI2 mRNA levels." (PMID 37251370, 2023). "SNAI2 (Snai2) is a member of this family, participating in numerous types of biological regulation processes, including epithelial–mesenchymal transition (EMT), cancer metastasis, and cellular reprogramming." (PMID 36674577, 2023). "Slug (also known as SNAI2), a member of the SNAIL superfamily of zinc-finger transcription factors, plays a pivotal role in modulating the expression of genes responsible for the EMT during embryogenesis and cancer." (PMID 35655230, 2022). "In malignant tumors, transcription factors like ZEB1 and ZEB2, SNAI1 and SNAI2, and Twist-related protein (TWIST) 1 and 2 may lead to migratory and invasive cancer cells." (PMID 35463825, 2022). "Studies have shown that Wnt/β-catenin signaling could upregulate the expression of Slug (Snai2), ZEB1, and ZEB2 in cancer cells, thereby reducing the level of E-cadherin to promote cell migration." (PMID 36398031, 2022). "However, in the case of combined Selumetinib- and Trametinib-resistant cancers, FN1 and CD44 were down-regulated; TIMP1 and SNAI2 were down-regulated only in Selumetinib-resistant ones; while SPARC was down-regulated in the case of Trametinib-resistant cancer." (PMID 35534592, 2022). "From our big data studies validated with independent datasets, protein-coding hub genes FN1, CD44, TIMP1, SNAI2, and SPARC were found significantly enriched in signal transduction, proteolysis, cell adhesion and proteoglycans pathways in cancer as well as the PI3K/Akt-signaling pathway." (PMID 35534592, 2022). "This suggests that, in addition to their effect on SNAI2 and CDH gene expression, both DLK1 and DLK2 may affect other shared mechanisms that modulate the invasive properties of MDA-MB-231 and other cancer cells." (PMID 35163478, 2022).
cancer (continued). "However, SNAI2 and SNAI3 expression were downregulated and upregulated, respectively, in primary cancer cells." (PMID 35898399, 2022). "EMT is also associated with invasion in new tissues, supported by the upregulation of Snail Family Transcriptional Repressor 1 (SNAI1) and Twist Basic Helix-Loop-Helix Transcription Factor 1 (TWIST1) via Snail Family Transcriptional Repressor 2 (SLUG; SNAI2) regulation in different cancer types." (PMID 35574343, 2022). "SNAI2 and TWIST1 induce the stemness property of cancer cells." (PMID 34339740, 2021). "Moreover, other groups found that the CRL5–ASB13 complex degrades SNAI2 and the CRL5–SPSB3 complex degrades SNAIL to inhibit cancer metastasis." (PMID 34164402, 2021). "While the mesenchymal signal in simulated bulk expression profiles predominantly reflects the presence of CAFs, our analysis also identifies specific ESGs (e.g. SNAI2, SDC1/4 and LAMC2) whose expression levels in the cancer cells are higher than or comparable to those in CAFs." (PMID 33972543, 2021). "In patients with advanced BCs in advanced stage (TNM III and IV), downregulated miR-203a-3p, and SNAI2 with ZEB1 were detected in TU-C and TU-IF, and upregulation of SNAI1 and miR-205-5p was found in samples with disseminated cancer cells, LNM and CD45-DB fractions, respectively." (PMID 35008529, 2021). "Thus, the activation of cancer cell dissemination and subsequent formation of distal metastases via the MSC-stimulated expression of EMT markers can be triggered by Snail/Snai2 (Slug), Twist, vimentin and N-cadherin." (PMID 32751163, 2020). "Consistently, treatment of epithelial tumor cells with TSA or other HDAC inhibitors, such as suberoylanilide hydroxamic acid (SAHA) or valproic acid (VPA), can induce EMT in certain cancer cells, with an upregulation of EMT factors such as ZEB1, ZEB2 or SLUG (SNAI2)." (PMID 31277295, 2019). "Downstream transcription factors such as SNAI1, SNAI2, zinc finger E-box binding homeobox 1 and 2 (ZEB1 and ZEB2), TWIST1, Forkhead boxC2 (FOXC2), high mobility group A2 (HMGA2) and paired related homeobox 1 (PRX1) are subsequently activated in carcinoma." (PMID 31558913, 2019). "Estrogenic induction of mesenchymal markers SNAI1, SNAI2, and CDH2 expression, with a consequent increase in cancer cell migration, was shown to depend on CXCR7, indicating a key role for CXCR7 in mediating estrogen upregulation of mesenchymal markers to induce invasion of OC cells." (PMID 30051594, 2018). "Accordingly, silencing the expression of SNAIL and SLUG (Snail family transcriptional repressor 2), crucial EMT inducers, could sensitize cancer cells to genotoxic stress induced by chemo or radiotherapy." (PMID 28872613, 2017). "SNAI2, a member of the snail family of transcription factors, can promote cell invasion, motility, metastasis, and poor prognosis via inhibiting the E-cadherin transcription and inducing EMT in several human cancers." (PMID 27259250, 2016). "SNAI1, SNAI2, ZEB2, and VEGFA have been reported as miR-203 targets related to cancer invasion." (PMID 26882562, 2016). "As emerging regulators of cancer stemness, growth and malignant progression, the two closely related transcriptional regulators YAP1 and TAZ are drastically down-modulated by SNAI2 gene silencing, whereas TAZ in particular is also up-regulated by SNAI2 over-expression." (PMID 25686823, 2015). "Consistent with expectations, canonical luminal genes such as ESR1, GATA3, FOXA1, TFF1 and IGF1R were higher in ER+ samples compared to triple negative samples, while proliferation and mesenchymal genes such as SPRY2, SNAI2, FOSL1, MET and BUB1 were higher in triple negative cancers." (PMID 24520381, 2014). "The miR-138-mediated decrease of FOSL1 protein level also determines a down-regulation of the transcription repressor gene Snail homolog 2 (SNAI2) and, as a direct consequence, an enhanced E-cadherin expression, which prevents epithelial-to-mesenchymal transition and cancer progression." (PMID 23271365, 2012).
cancer (continued). "Moreover, our epithelial-to-mesenchymal transition (EMT) analysis revealed a consistent inverse association between PEBP1/STK11 co-expression and EMT marker genes, including SNAI1, SNAI2, FOXC2, ZEB1, and FN1, across most cancer types examined, thus underscoring a uniform anti-EMT signature." (PMID 40806276, 2025). "However, the role of SNAI2 in cancer immune infiltrations and immunotherapy response prediction is not clear, and no comprehensive pan-cancer study has been performed yet." (PMID 37251370, 2023). "Furthermore, miR-662 overexpression in MDA-MB-231 cells substantially increased mRNA expression levels of stemness markers involved in embryogenesis and cancer, such as NOTCH1, WNT7b, ZEB1, TCF3, and SNAI2, reinforcing the notion that miR-662 expression enhanced stem-like properties of BC cells." (PMID 37443350, 2023). "Therefore, our study found that SNAI2 might play a potential role in affecting MMR regulation and DNA methylation in various cancers." (PMID 37251370, 2023). "Consistently, analysis of the RNA-seq data from another independent study (GSE92250) also showed that ELF3-AS1 knockdown led to SNAI2 mRNA upregulation in the A549 and Hela cell lines, suggesting the negative regulation of SNAI2 expression by ELF3-AS1 might be widely in cancers." (PMID 36457025, 2022). "In addition, we also analyzed the correlation between NUTF2 and the epithelial–mesenchymal transition (EMT) markers, Vimentin (VIM), TWIST1, Snail1 (SNAI1), Snail2 (SNAI2), Fibronectin 1 (FN1), and N‐cadherin (CDH2), which were widely accepted to be involved in cancer metastasis." (PMID 35155261, 2022). "Therefore, taken together, the elevated SNAI2 and SOX9 protein levels may also have greatly contributed to the up-regulation of cancer stem cell features and motility of those DU145FP cells." (PMID 28698547, 2017). "Because SNAI2 has been implicated in EMT and in the invasive metastatic behavior of breast and other cancer cells we employed the MCF7/Rx2dox culture system to test the hypotheses that Runx2 induces and E2 antagonizes EMT and invasiveness, and that SNAI2 plays a role in these processes." (PMID 22151997, 2011). "Further, this analysis also strongly suggested that SNAI2, SUZ12 and HDAC1 might form a repressor complex, implicating the interaction of transcriptional factors and histone modification regulators to have a pivotal role in miR-204-5p-mediated inhibition of cancer progression." (PMID 31938073, 2020). "Moreover, activation of several FGF downstream signaling pathways was also observed including cancer related pathways (RAS-MAPK, PIK3-AKT, and STAT) with a significant upregulation of several key molecules in these pathways (e.g., BIRC5, RAF1, MYCN, IGF2, SNAI2, POSTN)." (PMID 31477684, 2019). "Although SNAI2 inhibition could promote proliferation of non-cancer hepatic HL-7702 cells, alteration of SNAI2 expression did not influence the proliferation of MHCCLM3 cells under regular culture conditions (data not shown), which was consistent with previous report." (PMID 27760172, 2016). "SNAI2 expression was immunohistochemically assessed to validate molecular data at the protein level, and also visualize any fluctuation (suggested by the lack of methylation in some of the microdissected cancer cell populations) of its expression within the heterogeneous prostate tissue." (PMID 25686823, 2015). "We found that cancer cells overexpress epithelial-to-mesenchymal transition markers TWIST1 and SNAI2, as well as stem-like marker CD44 (but not CD133, SOX2 and/or NANOG)." (PMID 33531664, 2021). "We showed that SNAI2 could recruit EZH2 but not SUZ12, suggesting SNAI1 and SNAI2 have different functions and non-overlapping roles in cancer cells and might cooperate to recruit PRC2 to the CDH1 promoter." (PMID 31938073, 2020).
adenocarcinoma (5 papers, 2015 to 2021). A common cancer characterized by the presence of malignant glandular cells. "Heatmap analysis revealed upregulated VIM and PLK1 mRNA expression in TGF-β-treated adenocarcinoma when the mesenchymal markers CDH2, SNAI1, and SNAI2 were high and either CDH1 or OCLN (epithelial markers) was low in majority of LUAD cells analysed." (PMID 33963314, 2021).
infection (4 papers, 2014 to 2024). The state of being infected such as from the introduction of a foreign agent such as serum, vaccine, antigenic substance or organism. "Furthermore, decreased expression of transcriptional factor (SNAI1, SNAI2) during pathogen infection may suppress VIM expression and reduce pathogen translocation into the cells." (PMID 34372621, 2021).
prostate (4 papers, 2015 to 2025). "Since DNA methylation marks the entire spectrum of prostate carcinogenesis, we next tested its involvement in the loss of SNAI2 gene expression in PCa." (PMID 25686823, 2015). "Consequently, we selected eight statistically significant TACTs—EPCAM, KRT19, ERBB2, MKI67, MCAM, FOXA2, SNAI2, and NPTN—which we designated as colorectal TACTs (C-TACTs)." (PMID 40003943, 2025).
neurologic diseases (1 paper, 2022). "Furthermore, among these EMT genes, four genes (MMP2, MAP1B, SNAI2, and WNT5A) were involved in neurologic diseases." (PMID 36553576, 2022). "Interestingly, four EMT genes (MAP1B, SNAI2, MMP2, WNT5A) are also involved in neurological diseases, in brain metastasis, and interact with platinum-based chemotherapy and tyrosine–kinase inhibitors." (PMID 36553576, 2022). "Interestingly, four EMT genes (MAP1B, SNAI2, MMP2, and WNT5A) were also involved in neurological diseases, brain metastasis, and response to platinum-based chemotherapy or tyrosine–kinase inhibitors." (PMID 36553576, 2022).
SNAI2 also shares sentences with these, for which no sentence is quoted: esophageal squamous cell carcinoma (8 papers); atherosclerosis (4); endometriosis (4); esophageal cancer (4); pulmonary hypertension (3); acute myeloid leukemia (2); Barrett esophagus (2); benign prostatic hyperplasia (2); brain disease (2); germinoma (2); Hepatic fibrosis (2); hyperglycaemia (2); invasive ductal carcinoma (2); meningioma (2); metastatic prostate carcinoma (2); nasopharyngeal carcinoma (2); rhabdomyosarcoma (2); sarcoma (2); tongue SCC (2); acute leukemia (1); adenoma (1); Alzheimer disease (1); anaplastic cancer (1); Angelman syndrome (1); arteriosclerosis (1); arteriosclerotic cardiovascular disease (1); astrocytic tumor (1); basal cell carcinoma (1); benign meningioma (1); benign neoplasm (1).
A further 73 diseases each share a sentence with SNAI2 in 1 paper.